CASP8 (caspase 8)
Diseases named in the same sentence as CASP8 in open-access papers (continued):
Sharing a sentence is not in itself a finding about the gene and the disease.
Sepsis (continued). "However, they found three markers, E3 ubiquitin-protein ligase (TRIM21), Pleiotrophin (PTN), and Caspase-8 (CASP8), that differentiated COVID-19 from community-acquired pneumonia sepsis more accurately than standard clinical markers." (PMID 39859366, 2025). "Furthermore, neutrophils extracted from the blood of patients who have suffered from sepsis or polytrauma can induce the apoptotic death of other cells by the dephosphorylation of Caspase-8 on the epithelial cell." (PMID 36358327, 2022). "We report that BM-derived megakaryocytes and blood platelets both express TLR4 on their surface, as assessed via flow cytometry, prompting us to assess the effect of loss of Caspase-8 and MLKL on platelet production and clearance in an in vivo LPS-induced sepsis model." (PMID 33510145, 2021). "However, Nec-1 has currently been found to increase apoptosis in hepatocytes after sepsis, most likely by enhancing the cleavage of caspase 3 as well as caspase 8 and 9 activities." (PMID 31527653, 2019). "Hence, a complete block of caspase-8 during an immune response in vivo is likely to result in hyper-inflammation and increased induction of sepsis." (PMID 25474208, 2014). "Therefore we used co-immunoprecipitation and immunoblotting to examine the effects of AdHSP on the sepsis-induced formation of complexes containing pro-caspase 3, caspase 8 and caspase 9, as well as Apaf-1." (PMID 22132083, 2011). "Inhibition of Fas or silencing of caspase-8 inhibits apoptosis during sepsis." (PMID 18925930, 2008). "Studies have reported that cytokines (TNF-α, IL-10, and TGF-β) could regulate apoptosis by regulating the activity of caspase-8 in the death-induced signaling complex or changing death or survival factor levels, which control the Fas apoptotic pathway in sepsis." (PMID 33954185, 2021). "We observed prominent necroptosis activation in sepsis—evidenced by elevated RIPK-1, IL-1β, and IL-18 levels and suppressed caspase-8 levels." (PMID 40722817, 2025). "This study underscores the pivotal role of necroptosis in the pathophysiology of sepsis, as reflected by elevated levels of RIPK1, IL-1β, and IL-18 and reduced expression of caspase-8 across both pediatric and adult patients." (PMID 40722817, 2025). "Our study uncovers a role for RIPK3/caspase-8 signaling in regulating obesity-induced inflammation, independent of its capacity to activate NLRP3, aligning with recent reports in sepsis and arthritis models." (PMID 39532538, 2025). "Our findings revealed a notable increase in the expression of ASC/caspase-8/RIPK3, key PANoptosis proteins, within T cells during sepsis." (PMID 40995563, 2025). "C57BL/6 wild type (WT), Casp8−/−, Ripk3−/−, and Zbp1−/− mice were subjected to the cecal ligation and puncture (CLP) sepsis model." (PMID 39465383, 2024). "The volcano plot and heatmap indicated that JAK3, CHMP5 and IFNAR1 were upregulated while CASP8, VDAC2, FASLG, JAK1, STAT4 and BCL2 were downregulated in sepsis." (PMID 38894720, 2024). "Our data showed that pro-apoptotic proteins, Fas, Fas-L and cleaved caspase-8 were remarkably upregulated at day 1 after CLP, but declined to near sham levels at day 3 after sepsis." (PMID 30052667, 2018). "In addition, the plasma proteome alterations identified unique features associated with respective disease, allowing the discovery of potential plasma biomarkers for differential diagnosis of COVID-19 and CAP-sepsis, among them TRIM21, PTN and CASP8." (PMID 36829233, 2023). "Finally, through machine learning, we identified biomarkers, such as TRIM21, PTN and CASP8, that accurately differentiated COVID-19 from CAP-sepsis with higher accuracy than standard clinical markers." (PMID 36829233, 2023). "Moreover, transcript levels of the pro-apoptotic genes BAK1, CYCS, BBC3, CASP7, and CASP8 were upregulated in the COVID-19 cohort, whereas those of anti-apoptotic genes, such as BCL2L11 and BCL2L1, were upregulated in the sepsis cohort." (PMID 36443881, 2022).
COVID-19 (34 papers, 2020 to 2025). A disease caused by infection with severe acute respiratory syndrome coronavirus 2. "Necroptosis is an immunogenic type of cell death that can cause inflammatory reactions by releasing inflammatory cytokines and molecular patterns that are linked to cell damage (DAMPs), such as that caused by CASP8 in severe COVID-19." (PMID 36851766, 2023). "A study found that TNF-α and IFN-γ synergism mediated RIPK1/FADD/CASP8 axis-derived PANoptosis in murine bone marrow-derived macrophages (BMDMs) drives pathology in COVID-19 and other diseases associated with cytokine storm." (PMID 34594225, 2021). "COVID-19 investigations have revealed that caspase-8 levels are substantially elevated, which confirms that the virus activates the programmed cell death mechanisms, resulting in the demise of COVID-19 virus-infected cells." (PMID 40431570, 2025). "In line with the current health issues emerging from the long-term effects of COVID-19, we observed elevated caspase-8 levels in the lungs of recovered animals at least up to 1-month post-infection." (PMID 41233351, 2025). "Using gene-targeted murine COVID-19 models, we here find that caspase-8 is critical for cytokine release and inflammation." (PMID 41233351, 2025). "Activation of Caspase-3 and Caspase-8, as well as overexpression of Bax and Bak (proapoptotic proteins of the Bcl-2 family), have been demonstrated in T cells from COVID-19 patients." (PMID 40943325, 2025). "In line with previous studies in COVID-19 patients, this increase in caspase-8 also occurred in infected human lung tissue explants in vitro." (PMID 41233351, 2025). "Compared to COVID-19 monocytes, there was indeed significantly increased active caspase 8 levels in MIS-C samples." (PMID 38762592, 2024). "Using machine learning, we identified a set of diagnostic plasma biomarkers (e.g., TRIM21, CASP8, PTN and CSF1) that had very high accuracy in differentiating COVID-19 from CAP, and outperformed standard laboratory parameters used in clinical practice." (PMID 36829233, 2023). "Furthermore, deletion of nitric oxide synthase 2 (Nos2) or Casp8, another key molecule in PANoptosis, reduces SARS-CoV-2 infection-driven weight loss without impacting peak viral burdens in mice, suggesting there may be a pathogenic role for the iNOS-caspase-8 axis in COVID-19." (PMID 36419185, 2022). "Junqueira at al identified increased expression of RIPK3, ZBP1 and Caspase-8 in blood samples of severe COVID-19 cases using expression quantitative trait loci (eQTLs) gene profiling." (PMID 35244141, 2022). "We found that FLIP, a protein that controls caspase-8 death pathways, was highly expressed in myeloid cells of COVID-19 lungs." (PMID 34518653, 2022). "Genetic loss of caspase-8 reduces cytokine levels, lowers viral load and mitigates disease severity, revealing non-apoptotic caspase-8 as a key driver of severe COVID-19." (PMID 41233351, 2025). "Multiple studies suggest the involvement of Caspase-8 in pathogenesis of COVID-19." (PMID 35244141, 2022). "Molecules such as c-FLIP or NF-kB inhibitors or caspase-8 activators could be studied and eventually included among the drugs used to contrast COVID-19." (PMID 34201847, 2021). "Also of interest is that sustained upregulations of HGF, TNFSF14 and CASP-8 have been observed in studies on COVID-19 patients as an indicator for severe disease." (PMID 34948231, 2021). "The SARS-CoV-2 infection triggered a dual mode of cell death pathways and caspase-8-dependent inflammatory responses may lead to the lung damage in the COVID-19 patients." (PMID 33037188, 2020). "Interestingly, a recent study on caspase-8 suggests, consistently, that caspase-1 might also assist towards the development of therapeutic strategies to treat COVID-19." (PMID 35163769, 2022). "Therefore, we conclude that CASP3 and CASP8 may be activated and play an important role in the pathophysiological process of COVID-19." (PMID 33029094, 2020).
COVID-19 (continued). "Individuals with severe COVID-19 had higher FASL expression and higher caspase-8 activity in CD4+ and CD8+ T cells." (PMID 39859379, 2025). "Early in the COVID-19 outbreak, SARS-CoV-2 was shown to trigger the caspase-8-dependent death of lung epithelial cells." (PMID 35997950, 2022). "Co-targets were 194 genes intersecting with COVID-19, RA-DEGs (GSE55235), and pyroptosis-related genes, including 7 genes: CASP1, CASP8, IL1B, CASP3, JUN, EGFR, CXCL8." (PMID 36532040, 2022). "In support of histological evidence of lung epithelium damage, concentrations of cell death–related proteins tumor necrosis factor–α (TNFα), caspase 8, TRAIL, EDAR, and NCR1 were altered in plasma from patients with COVID-19 relative to normal controls." (PMID 34648357, 2021). "Collectively, these findings highlight non-apoptotic functions of caspase-8 as a driver of severe COVID-19 through modulation of inflammation, not through the induction of apoptosis." (PMID 41233351, 2025). "Interrogating expression of individual markers, we found five notable proinflammatory analytes (Caspase-8, EN-RAGE, IL-18, MCP-3, and MMP-1) that were present at higher concentrations in the supernatants of severe COVID-19 patient monocyte cultures compared with healthy monocyte cultures." (PMID 38578283, 2024). "During SARS-CoV-2 infection, inhibition of Caspase-8 resulted in decreased IL-1β secretion, but not less viral replication, suggesting the involvement of Caspase-8 in pro-inflammatory signaling during COVID-19." (PMID 35244141, 2022). "The deletion of both RIPK3 and caspase-8 is found to protect against cell death, not RIPK3 deficiency only, which shows that not only necroptosis but also other processes of cell death occur in COVID-19." (PMID 34594225, 2021). "In addition to these three markers, the ICU group tend to be separated from non-ICU patients by OSM and S100A12, whereas all COVID-19 patients can be distinguished from healthy controls by CASP8, IFNγ, IL-18R and CCL8." (PMID 33239683, 2020).
oral cancer (32 papers, 2004 to 2025). "In concordance with previous reports, we observed higher mutation frequency in CASP8 gene in oral cancer patients." (PMID 34136393, 2021). "Mutations in CASP8 are reported to be higher in oral cancer tissues than in leukoplakia tissues and can be used to profile progression of leukoplakia to oral cancer." (PMID 34136393, 2021). "Further, studies on oral cancer cell lines showed that inactivating mutation in CASP8 can confer tumors with clonal growth advantage and increased cell migration." (PMID 32492030, 2020). "In a syngeneic mouse model of oral cancer, birinapant, particularly when combined with radiation, delayed tumor growth and enhanced survival under CASP8 loss." (PMID 33108350, 2020). "Here, we found that CASP8 mutation may emerge as a potential signature for progression of oral cancer from leukoplakia." (PMID 32492030, 2020). "The study implies that CASP8 mutation could be one of the signatures for some of the leukoplakia to progress to oral cancer." (PMID 32492030, 2020). "Exome sequencing of oral cancers, a subset of Head and Neck Squamous cell Carcinomas (HNSCs) common among tobacco-chewing populations, revealed that ∼34% of the affected patients harbor mutations in the CASP8 gene." (PMID 30775178, 2019). "Additionally, Lico-A-induced apoptosis in KB oral cancer cells was mediated by the expression of factor associated suicide ligand (FasL) and activated caspase-8 and −3 and poly(ADP-ribose) polymerase (PARP)." (PMID 24337492, 2014). "Oral cancer cells exhibited higher activated caspase 8 (+) (%) with X-ray/SK2 treatment than with the others." (PMID 38398060, 2024). "Previous studies have shown that the caspase-8/Bid pathway can trigger apoptosis in oral cancer cells." (PMID 38068849, 2023). "UVC/SK2 showed higher caspase 8 and caspase 9 (+) counts in oral cancer cells (Ca9-22 and OC-2) than in single treatment." (PMID 35625933, 2022). "Evaluation of the combination of six genes with aberrant methylation (RARB, KLLN, CHFR, TP73, GSTP1, and CASP8) was particularly useful for identifying early-stage oral cancer in clinically diagnosed patients with OPMDs with high diagnostic performance." (PMID 35681626, 2022). "In this study we demonstrated that ginsenoside M1 induces the activation of two initiator caspases, caspase-8 and caspase-9 in human oral cancer cells." (PMID 33352689, 2020). "In oral cancer CAL 27 cells, GSE also reported to induce mRNA overexpression of apoptosis-associated signaling such as caspase-2 and caspase-8." (PMID 25880412, 2015). "This suggests that activated caspase-8 in the extrinsic apoptosis signaling pathway can affect the intrinsic mitochondrial-dependent apoptotic signaling pathway in KB oral cancer cells." (PMID 25634589, 2015). "Our data also suggest that the activator caspase-8 is an integral component of the cell death-inducing mechanism in oral cancer cells, in agreement with other studies." (PMID 15613236, 2004). "Notably, X-ray/SK2 treatment exhibited higher activated caspase 8 (+) (%) in oral cancer cells than in normal cells, i.e., 87.5%, 92.2% vs. 47.0% for Ca9-22, CAL 27 vs. S-G, respectively." (PMID 38398060, 2024). "Our results shed light on the functional significance of Caspase-8 in oral cancer." (PMID 39625985, 2024).
oral cancer (continued). "We confirmed previous observations that laryngeal and pharyngeal cancers rarely harbor CASP8 and HRAS mutations in comparison to oral cancers – in our comparison, these alterations were almost completely absent in hypopharyngeal tumors when juxtaposed with other head and neck cancer subtypes." (PMID 35664801, 2022). "We found that a combination of six genes (TP73, CASP8, RARB, KLLN, GSTP1, and CHFR) could distinguish oral cancer from clinically diagnosed OPMDs with high diagnostic performance (area under the curve [AUC], 0.885; sensitivity, 77.8%; and specificity, 87.1%)." (PMID 35681626, 2022). "Based on Sanger sequencing method, another study on Southern Indian patient populations, reported 8% of oral cancer tissues had CASP8 mutations but none in oral sub-mucous fibrosis tissues (another oral precancerous lesion)." (PMID 32492030, 2020). "Using Sanger sequencing method, a study reported absence of CASP8 mutation in oral cancer samples collected from South Indian patients." (PMID 32492030, 2020). "CASP8 mutations with or without FAT1 mutations have been used as an important criterion for classifying mutational profiles of oral cancer patients." (PMID 32492030, 2020). "The curcumin analog HO-3867 has been shown to activate caspase 3, caspase 8, caspase 9, and PARP via the JNK pathway, resulting in the apoptosis of human oral cancer cells." (PMID 40002335, 2025). "Pretreatment with the JNK1/2 inhibitor (JNK-IN-8) and p38 inhibitor (SB203580) effectively reversed the expression of cleavage caspase-8, -9, and -3, and HO-1, compared with the magnolol-only-treated HSC-3 oral cancer cells." (PMID 34680412, 2021). "Quercetin treatment induced apoptosis in human oral cancer SAS cells by increasing the expression of Fas, Fas-Ligand, and caspase-8." (PMID 32093300, 2020). "The mRNA expression of caspase-3, caspase-8 and caspase-9 in HSC-3 oral cancer cells were analyzed by RT-PCR and Western blot assays." (PMID 25951128, 2015). "Previous genomic data have begun to reveal subgroups of oral cancers with distinct molecular profiles and unique molecular drivers, including a subgroup of CASP8 (OMIM 601763) patients with or without FAT1 (OMIM 600976) mutations." (PMID 40974176, 2025). "Fucoidan showed subG1 accumulation and an annexin V increase in apoptosis, accompanied by caspase 8, 9, and 3 activations in oral cancer cells, but not in S–G cells." (PMID 35624705, 2022). "Consistently, in HSC‐3 cells, HO‐3867 reduced the pro form of caspase 8, caspase 9, caspase 3 and PARP, and enhanced the active form of caspase 8, caspase 9, caspase 3 and PARP These results imply that HO‐3867 induces apoptotic pathway through caspase pathway in human oral cancer cells." (PMID 35191177, 2022).